RN7SL868P (RNA, 7SL, cytoplasmic 868, pseudogene)
Gene: Miscellaneous RNA gene on chromosome 5 (149,722,070 to 149,722,372, forward strand). Ensembl gene ENSG00000242928.
Homologues: Orthologues: chimpanzee Metazoa_SRP (99% identical), macaque Metazoa_SRP (97% identical). Paralogues in human: RN7SL1 (82% identical), RN7SL2 (81% identical), RN7SL3 (80% identical), RN7SL448P (80% identical), RN7SL220P (79% identical), RN7SL509P (79% identical), RN7SL655P (79% identical), RN7SL709P (79% identical), RN7SL88P (79% identical), RN7SL320P (78% identical), RN7SL344P (78% identical), RN7SL618P (78% identical), and 702 more.